MMP9 (matrix metallopeptidase 9)
Diseases named in the same sentence as MMP9 in open-access papers (continued):
Sharing a sentence is not in itself a finding about the gene and the disease.
cancer (continued). "Studies show increased expression of MMP-9 which is associated with invasion, metastasis, and poor prognosis in various cancers including cervical, colorectal, ovarian, and breast cancer." (PMID 34707964, 2021). "Together, these data provide compelling in vitro and in vivo evidence showing novel mechanisms underlying the IL‐33‐macrophage‐MMP‐9 axis‐mediated immune tolerance against cancer cells." (PMID 34486239, 2021). "Since MMP-9 and VEGFA have been implicated in the progression and metastasis of various cancers, western blot assessment was employed to measure the expression of MMP-9 and VEGFA in HCC cells treated with BJJP." (PMID 33762939, 2021). "Several MMP-specific inhibitors have been found to significantly inhibit the proliferation of many cancer types, particularly MMP9, for which inhibition has been associated with promising outcomes in BC." (PMID 34834261, 2021). "A real-time quantitative reverse transcription-PCR (qPCR) analysis recorded a decrease in the mRNA levels of both vascular endothelial growth factor receptor-2 (VEGFR2) and MMP-9, two key regulators of cancer-associated angiogenesis." (PMID 33498927, 2021). "Previous studies revealed that increased expression of MMP-9 is associated with poor prognosis in patients with several types of cancer and increased invasion and metastasis of cancer cells." (PMID 34769032, 2021). "Given the promiscuity of galectins for multiple glycosylated cell-surface receptors, it is likely that the signals implicated in the upregulation of MMP-9 involve multiple receptors that vary according to the cancer subtype." (PMID 34198494, 2021). "Matrix metalloproteinase 9 (MMP9) is associated with the progression and invasion of malignant tumors." (PMID 34853307, 2021). "In cancers, increased levels of MMP9 has been associated with tumorigenesis and metastasis;40, 41 however, in PE their expression is down‐regulated." (PMID 33942999, 2021). "Accumulating reports show that overexpression of certain MMPs (e.g. MMP2, MMP3 and MMP9) is associated with EMT during cancer initiation and progression." (PMID 33931048, 2021). "MMP9+/MMP2+/EMMPRIN+ subpopulation of CD9-positive blood plasma exosomes reduced the cancer risk in CPPs." (PMID 33773551, 2021). "Metastasis, migration and invasion associated cancer genes such as RanGAP1 (Ran-GTPase activating enzyme 1), Rho-like GTPase- Rac1, MMPs like MMP-9, MMP-14 and slug are found to be profoundly SUMOylated." (PMID 34715855, 2021). "Previous studies showed that MMP‐9 polymorphisms were associated with increased risk of IS, cancer, and hemorrhagic transformation of IS." (PMID 31909567, 2021). "Overexpression of marker like MMP-9 is linked to the rapid progression of tumorigenesis and poor overall survival of cancer patients due to metastasis." (PMID 33112542, 2020). "We focussed our evaluation of driver mechanisms underpinning our observations on the immunological effects of MAPK7 loss, as seen in other cancer models, and the interaction with MMP9 signalling therein." (PMID 32655131, 2020). "Since MMP-9 is strongly associated to inflammation, wound healing and cancer migration, these results are more consistent to the anecdotal reports on Aloe bioactivities." (PMID 33308217, 2020). "Deregulated MMP-9 expression and/or activity causes cellular invasiveness and leads to the growth and clinical progression of a wide variety of human cancers." (PMID 32630531, 2020). "By contrast, the cancer cell invasion was rescued by transfection with siMMP-9 (which caused a knockdown of MMP-9)." (PMID 32238777, 2020). "Many studies have reported an association between elevated MMP-9 levels and increased rates of cancer metastasis and poor clinical outcomes." (PMID 32698816, 2020). "MMP2 and MMP9 are closely associated with cancer metastasis due to their strong proteolytic activity of the ECM (extracellular matrix)." (PMID 32650804, 2020).
cancer (continued). "SPOCK1, TGF-β1, and MMP-9 are associated with the EMT process in several cancer types so, we asked if these molecules are also involved in EMT-related DIGO." (PMID 32555336, 2020). "MMP-9 is most widely associated with cancer progression, due to its role in extracellular matrix remodeling and angiogenesis." (PMID 32326231, 2020). "The epigenetic alterations of both VEGFa and MMP-9 mediated by hsa-miR-155-5p were finally responsible for the phenotypical switch of fibroblasts towards a cancer-associated fibroblast phenotype known to be associated with angiogenesis." (PMID 32392801, 2020). "This resulted from inflammation associated NETosis in which the proteases, MMP-9 and elastase expressed on NETs caused proteolytic remodeling of laminin, which, in turn, triggered the proliferation of dormant cancer cells via binding to the integrin α3ß1." (PMID 32244751, 2020). "Amongst all MMPs, overexpression of MMP‐9 in particular indicates a higher risk of poor prognosis and poor survival in various cancers." (PMID 33021341, 2020). "MMP9 is often overexpressed in malignant tumors and is associated with aggressive malignant phenotypes and poor prognosis in cancer patients." (PMID 32936304, 2020). "In the previous studies, overexpression of MMP-9 has been reported to be associated with higher grade, metastasis, and angiogenesis in a large number of human cancers." (PMID 32382550, 2020). "The finding of increased EMMPRIN secretion with the associated increase of MMP-9 secretion suggests a higher metastatic potential, since their increased expression was correlated in several different cancers and is a poor prognostic indicator." (PMID 32948029, 2020). "Currently, a particular group of matrix metalloproteinases (MMPs) named gelatinases (MMP-2 and MMP-9) is greatly associated to cancer invasion through degradation of the cellular matrix, and the consequent release of cancer cells via proteolysis." (PMID 33308217, 2020). "As a transcription factor, FOXM1 has many target genes including KIF20A, CENPF, CCNB1, MYC, NIMA-related kinase 2, MMP2, MMP9, and S-phase kinase-associated protein 2 that are implicated in cancer initiation, progression, or drug resistance." (PMID 31072351, 2019). "As a consequence, we found cancer stem cell-associated proteins, such as mmp2, mmp9, mmp13, mmp14, paxillin, Ras, src and c-myc, as well as genes expressed in the immune system, such as C5, C9, and HMGB1." (PMID 31832023, 2019). "In most cancers, there are increased levels of one or several members of the MMPs and, in particular, MMP-9 is closely associated with the invasive and metastatic potential of most types of solid cancers." (PMID 30669448, 2019). "High MMP9 mRNA expression levels were associated with the expression of genes involved in cancer progression: BRCA2, COL4A1 and ITGA6, and were also associated with high FABP4 mRNA expression levels." (PMID 31874999, 2019). "In contrast, the direct proteolytic cleavage of osteopontin (OPN) by MMP-9 contributes to cancer metastasis, most likely associated with angiogenesis via the regulation of VEGF and angiostatin secretion." (PMID 31921634, 2019). "It has been reported that MMPs are major components involved in metastasis, especially, the increased MMP2 and MMP9, two important members of MMPs, are associated with cancer aggressiveness and metastasis in TNBC." (PMID 31186039, 2019). "MMP-9 levels in the peripheral circulation have also been shown to be associated with metastasis and long-term prognosis in a variety of cancers." (PMID 31038586, 2019). "Infections by P. gingivalis and F. nucleatum have been proven to cause cancer through pathways of MMP9 and upregulation of cytokines such as TNF-α, IL-1β, and IL-6." (PMID 31297102, 2019). "Metalloproteases secretion, in particular MMP-2 and MMP-9, is linked to invasive and metastatic properties of cancers cells." (PMID 31671408, 2019).
cancer (continued). "Among MMPs, MMP-2 and MMP-9 upregulation has been associated with invasive tumors, and they are considered to play an important role in invasion and metastasis formation of cancer cells." (PMID 30235821, 2018). "Evaluating the role of MMP-9 along with BRAF mutation can be useful in predicting the outcome of many cancers, especially PTC." (PMID 30509240, 2018). "The study of Kothari and associates demonstrated that IL-6 induces macrophage expression of MMP-9 via Cox-2-dependent and Cox-2-independent mechanisms, which has been directly associated with the pathogenesis of chronic inflammatory diseases and cancer." (PMID 30154846, 2018). "It was previously shown that IL-17A is associated with an increased expression of MMP-9, leading to enhanced cancer invasiveness and metastasis." (PMID 29983876, 2018). "LMP1 is found to be associated with activation of matrix metalloproteinase 9 (MMP9), which can degrade type IV collagen in the basement membrane to facilitate cancer invasion." (PMID 29617291, 2018). "MMP-2 and MMP-9 are both secreted, cancer-associated, zinc-dependent endopeptidases, which play key roles in regulation of some crucial signaling pathways in cell growth, invasion, migration, angiogenesis, and inflammation." (PMID 29899165, 2018). "To quantitatively analyze the association of IL-6 and metformin with cancer metastasis, we measured the expression of MMP9 by real-time polymerase chain reaction (qPCR)." (PMID 30308035, 2018). "Matrix metalloproteinase-9 (MMP-9) is associated with remodelling of the extracellular matrix and invasion in various cancers." (PMID 30142200, 2018). "Among them, MMP-9 (92 kDa type IV collagenase, gelatinase B) is produced from human macrophages and polymorphonuclear leukocytes and associated with numerous pathological processes including cancer, inflammation, placental malaria, and cardiovascular diseases." (PMID 30519264, 2018). "The results indicate that the GG and CC genotypes, respectively for both SNPs, are associated with increased risk of DVT in cancer patients by inducing the release of IL-6 with subsequent increment of MMP-9." (PMID 29872658, 2018). "MMP9, which plays a role in extracellular matrix remodeling and angiogenesis, is also associated with cancer metastasis." (PMID 30308035, 2018). "MMP-9 (gelatinase B), on the other hand, has been associated with numerous somatic illnesses, cardiovascular disorders, tumors, and cancers." (PMID 29518973, 2018). "As a consequence, MMP-9 is associated with many acute and chronic inflammatory diseases: from acute inflammation and shock syndromes to autoimmune diseases and cancer." (PMID 28369077, 2017). "Previous studies have revealed that PI3K/AKT/MMP9 pathway is closely associated with the process of cancer metastasis." (PMID 29296214, 2017). "MMP-9 is a class of enzymes that has been shown to be associated in cancer pathogenesis as they are involved in the degradation of extracellular matrix." (PMID 28160595, 2017). "First, many researches showed that high expression of MMP-2 and MMP-9 proteins are related with prognosis caused by cancer metastasis." (PMID 28350337, 2017). "Particularly elevated levels of MMP2 and MMP9 were found in various cancers as kidney and are associated to a poor prognosis." (PMID 29100286, 2017). "MMP9 is closely associated with cancer, due to its role in extracellular matrix remodeling and angiogenesis." (PMID 29179454, 2017). "Generation of activated forms of MMP2 and MMP9 was associated with cancer cell migration and invasion in vitro and in vivo." (PMID 27034162, 2016). "The proteolytic activity of MMPs involves the ECM degradation and evidences have shown that the expression of specific MMPs, such as MMP-2 (Gelatinase A) and MMP-9 (Gelatinase B), are associated with a wide range of human cancers." (PMID 27834913, 2016).
cancer (continued). "Overall, the results of the present study support the notion that MMP9 intragenic hypermethylation is associated with MMP-9 overexpression that in turn plays a role in cancer development and progression." (PMID 27115178, 2016). "MMP-2 and MMP-9 are implicated in photoaging and development of cancer and this study showed that 2% and 3% GTE inhibited expression of MMP-2 and MMP-9 post-UVR." (PMID 27618035, 2016). "Disruption of MMP-9- or γ-secretase–mediated N-cadherin cleavage downregulated MMP-9 and linked these processes to carcinoma invasion." (PMID 27737648, 2016). "Cancer-associated isoforms of MMP-9 bound galectin-3 in a rather reduced manner than natural MMP-9 did." (PMID 26528431, 2015). "A positive association was identified between the level of MMP-9 protein expression and the depth of cancer invasion (P<0.05)." (PMID 25621068, 2015). "It is well established in the literature that an increase in MMP9 expression levels is associated with increased cancer cell invasion." (PMID 25605249, 2015). "Growing evidence suggests that MMP-2 and MMP-9 are deeply implicated in CVDs and cancers through vascular remodeling and the formation of new blood vessels (angiogenesis and arteriogenesis)." (PMID 26637202, 2015). "Some have associated MMP-9 with the invasion and metastasis of many types of cancers like lung, breast, or colorectal cancer." (PMID 25821815, 2015). "It has been reported that MMP-2 and MMP-9 are overexpressed and implicated in promoting cancer cell invasion and metastasis in many cancers." (PMID 25402510, 2015). "A strong association between expression of FoxM1 and Cox-2 with MMP-9 expression has been reported in a number of cancers." (PMID 26159723, 2015). "Among the MMPs, MMP-2 and MMP-9 have been implicated in human cancer invasion, and we investigated the relationship between these two genes and miR-221/222 in this study." (PMID 25883224, 2015). "MMP2 and MMP9 are two of the most well-characterized MMPs and are closely associated with cancer invasion and metastasis due to their strong proteolytic activity of ECM." (PMID 24479681, 2014). "This inhibitory effect of administrated siRNA on L1CAM expression was strictly associated to decreased IHC staining of MMP-2, MMP-9 and NF-κb in cancer cells." (PMID 25294816, 2014). "Most significantly, MMP2 and MMP9 have been reported to cause invasion and metastasis in various cancers." (PMID 24348851, 2014). "MMP2 and MMP9 were selected as they have previously been implicated in the invasive ability of cancer cells." (PMID 24348851, 2014). "Among these proteases, the levels of MMP-2 and MMP-9 are high in various malignant tumors and are closely associated with the ability of cancer cells to invade and metastasize." (PMID 25036034, 2014). "Among several classes of degrading ECM proteinases, MMPs (MMP-2 and MMP-9) and urokinase-type plasminogen activator (uPA) have been closely associated with the metastatic phenotype of cancer cells." (PMID 25295247, 2014). "Polymorphisms in MMP1 −1607, MMP3 −1171 and MMP9 −1562 have been associated with general cancer metastasis in a large meta-analysis." (PMID 23696797, 2013). "The extracellular matrix proteins such as MMP-2 and MMP-9 which play an important role in cell migration and inflammatory processes associated with various cancers are highly induced in vehicle-treated xenograft tumors." (PMID 24260338, 2013). "Among the variety of MMPs, MMP2, MMP7, and MMP9 were more commonly associated with cancer metastasis as they have the ability to degrade collagen type IV which is the major component of basement membrane." (PMID 24138815, 2013). "MMP-2 and MMP-9 are the most extensively studied of the MMP family because of their high association with cancer migration and invasion." (PMID 23799155, 2013). "MMP-2 and MMP-9 were reported to be associated with the invasion and metastasis of many malignant tumors." (PMID 23613942, 2013).
cancer (continued). "MMP2 and MMP9 were significantly associated with cancer-related pathways, which further illustrates the potential of rhein and its products to be used for cancer relief in China." (PMID 23983798, 2013). "MMP-9 is associated with the aggressive nature of many cancers, including OSCC, and this aggressive nature was thought to cause type IV collagen degradation, a main component of basement membranes." (PMID 23365550, 2013). "Claudin-4 has been shown to activate MMP-2 and claudin-4 expression has been significantly associated with MMP-9 expression, indicating that claudin-mediated increased cancer cell invasion result from activation of MMP proteins." (PMID 23919729, 2013). "In many cancers, it has been shown that the high levels of matrix metalloproteinase (MMP)-2 and/or MMP-9 are associated with the invasive phenotypes of cancer cells." (PMID 23431332, 2013). "At the molecular level, MMP2, MMP7 and MMP9 are associated with cell migration process, influencing cancer development and progression." (PMID 24098538, 2013). "Its overexpression has been found to be associated with up-regulation of MMP-2 and MMP-9 that play an important role in cancer cell invasion and metastasis." (PMID 23922932, 2013). "The MMP family has 29 members; among these members MMP-2 and MMP-9 were found to have increased enzymatic activity and associations with metastasis in several cancers including NPC." (PMID 24243817, 2013). "MMP-2 is associated with local infiltration, while MMP-9 is the main participant in cancer recurrence and metastasis." (PMID 24137293, 2013). "One previous study has suggested that survivin, MMP-9, loss of heterozygosity, and altered DNA content are all potential markers for the progression from dysplasia to cancer." (PMID 23967071, 2013). "Polymorphisms in the MMP1, MMP2, MMP3, and MMP9 genes have been examined in studies evaluating cancer metastasis and functional polymorphisms have been identified for these genes." (PMID 23696797, 2013). "Among the MMPs family, MMP2 and MMP9 were more commonly associated with cancer invasion and metastasis since they had been known to be able to degrade type IV collagen-rich basement membrane of vessel wall." (PMID 24138815, 2013). "The oncogene, mouse double minute 2 (MDM2), has been implicated in the pathogenesis of numerous cancers, where it stimulates the expression of matrix metalloproteinase 9 (MMP9), an important enzyme in the breakdown of the extracellular matrix." (PMID 24236052, 2013). "Upregulation of the matrix metalloproteinases MMP-2 and MMP-9 in various cancers has been associated with worse survival of the patients." (PMID 22472880, 2012). "As a marker for BCa, studies have reported that elevated urinary protein levels of MMP-9 are associated with cancer." (PMID 22559832, 2012). "The functions of NF-κB in the transcription of the mesenchymal genes encoding VEGF, Vimentin, MMP-2 and MMP-9 are critical for promoting and maintaining a mesenchymal phenotype in cancers." (PMID 22640183, 2012). "Many studies have demonstrated that the upregulation of MMP-9 is associated with increased cancer cell migration and invasion." (PMID 23083134, 2012). "In our comprehensive meta-analysis, MMP1 (−1607)1G/2G, MMP7 (−181) A/G and MMP9 (−1562) C/T were shown to increase the risk of cancer metastasis, whereas MMP3 (−1171) 5A/6A was protective in metastasis." (PMID 22348060, 2012). "Previous studies have also identified significantly increased urine and plasma MMP-2 concentrations in cancer patients, with MMP-2 and MMP-9 being considered as predictors of risk or recurrence of metastasis or as cancer prognostic markers." (PMID 23320037, 2012). "One of the most interesting findings of the present study is that 4N1K expression is closely associated with MVD, cancer cell apoptosis, and MMP-9 expression, as determined via multivariate analyses." (PMID 22928942, 2012).